IGFBP7 (insulin like growth factor binding protein 7)
Diseases named in the same sentence as IGFBP7 in open-access papers (continued):
Sharing a sentence is not in itself a finding about the gene and the disease.
tumor (continued). "Moreover, IGFBP7 is negatively related to tumour grades and stages in HCC and can inhibit cell growth and promote senescence." (PMID 37660019, 2023). "Based on our speculation, we propose that α-SMA+, PDGFRB+, and IGFBP7+ CAFs play a role in tumor immunotherapy response." (PMID 37568781, 2023). "In tumor related research, IGFBP7 was first described mainly as a tumor growth suppressing factor." (PMID 37304887, 2023). "The results indicated that the protein expression of IGFBP6 and IGFBP7 could be detectable in all 20 types of tumor tissues." (PMID 37088808, 2023). "For example, IGFBP7 inhibits the expression of proteins associated with the activation of IGF signaling by binding to IGF-1 receptor and acts as a tumor suppressor, and IGFBP7 deficiency may promote HCC." (PMID 36293317, 2022). "In the TME, senescent tumor cells may increase antitumor immune responses by secreting IL-6, IL-8, and insulin-like growth factor binding protein 7 (IGFBP7) with the ability of recruiting immune cells such as T lymphocytes to the tumor site." (PMID 36518628, 2022). "Fourth, although IGFBP7 has been implicated as a tumor suppressor, we did not evaluate the function of IGFBP7 in reducing the carcinogenic effects of PTH, and further studies are needed to address these limitations." (PMID 35462909, 2022). "Host factors, including lifestyle, anthropometry and metabolic profile, might influence tumor-specific IGFBP7." (PMID 34606580, 2021). "As activated CAFs in carcinomas play an important role in tumor cell growth, invasion and metastasis, contrasting expression of IGFBP7 in tumor microenvironment (TME) cells may account for the divergent results in different studies." (PMID 33531979, 2021). "Among the genes under control of these dual modifications were known tumour-suppressor genes such as IGFBP7 (insulin-like growth factor binding protein 7) and SFRP1 (secreted frizzled-related protein 1), and callponin 3 (CNN3) associated with cytoskeleton maintenance." (PMID 34884658, 2021). "However, tumor-specific IGFBP7 levels appeared stable across ages in the BC Blood cohort and all adjusted models included age as a covariate limiting the risk of age confounding our results." (PMID 34606580, 2021). "Tumor-specific IGFBP7 levels in relation to other tumor characteristics." (PMID 34606580, 2021). "The activation of MAPK12 might be associated with the stress from the microenvironment and IGFBP7 may be related to tumor angiogenesis." (PMID 33808801, 2021). "This discovery suggests that IGFBP7 downregulation may be needed to mediate the tumor-promoting function of AEG-1." (PMID 32500027, 2020). "Interestingly, the existence of a tumor cell subpopulation and MyoCAFs that express high levels of IGFBP7 and MDK contributing to tipifarnib failure was unveiled by scRNA-seq in this study." (PMID 32460812, 2020). "For example, expression of IGFBP7 was insignificant in whole tumour analysis while homogenous stromal analysis showed significantly higher expression of IGFBP7 in both primary tumour and metastasis with 2.719 (p ≤ 0.05) and 12.46 (p ≤ 0.01) fold increase respectively when compared to normal stroma." (PMID 31959771, 2020). "IGFBP7 may also be a potential tumor endothelial cell marker, as identified by serial analysis of gene expression (SAGE)." (PMID 32500027, 2020). "New research indicates that IGFBP7 can suppress not only cancer cells but also modulate the tumor microenvironment, and this double effect may have a lasting impact on inhibiting both primary tumors and distant metastasis." (PMID 32500027, 2020). "Varied IGFBP7 expression patterns have been reported in different tumor types." (PMID 30609749, 2019). "Moreover, the proportion of proliferative Ki67-positive cells was significantly decreased in tumor tissues of IGFBP7-overexpressing xenografts and notably increased in IGFBP7-silenced tumor tissues." (PMID 31183073, 2019).
tumor (continued). "Most recently, the IGFBP7 protein has been identified as a novel biomarker of tumor fibroblasts." (PMID 30927930, 2019). "The mouse LUSC1 tumor was initiated from clonal cells having a mutant Igfbp7 gene, which may lead to an aberrant Igf-Igfr-Igfbp axis that is an important driver of cancer." (PMID 29484121, 2018). "Igfbp7 has been found to reduce tumor growth by induction of senescence and apoptosis pathways." (PMID 29673160, 2018). "TGF-β upregulates expression of IGFBP7 and angiogenic capacity of tumor cells." (PMID 28191313, 2017). "However, some changes were observed in the levels of expression of binding protein genes, with a decrease in IGFBP2, IGFBP3, and IGFBP4 expression and an increase in IGFBP7 expression with tumor progression." (PMID 28882129, 2017). "Furthermore, univariate and multivariate analyses showed that the AJCC stage of tumor and methylation status of IGFBP-7 was significantly correlated with DFS." (PMID 25880247, 2015). "Treated A253 cells with 5′AZA can inhibit IGFBP-7 promoter methylation and renovate the expression of IGFBP-7 but might also cause the re-expression of other tumor suppressor genes since 5′AZA is considered as an anti-tumor agent." (PMID 25880247, 2015). "Findings of IGFBP-7 downregulation in several tumor cell lines and its high expression in senescent cells suggest that it may also exert tumor-suppressive or anti-proliferative activity in normal tissue." (PMID 25594438, 2015). "Moreover, IGFBP-7 methylation status of 47 oral tongue tumors showed a positive correlation to invasive depth of the tumor, loco-regional recurrence, and cancer sequence." (PMID 25880247, 2015). "IGFBP7 has been described as tumor suppressor in several human cancers." (PMID 26450156, 2015). "Given the known tumour suppressor activity of IGFBP7 in several cancer types, understanding the importance of maintaining low/absent levels of IGFBP7 in HGSC is warranted to further elucidate the role of this protein in the development and progression of this disease." (PMID 25886299, 2015). "In vivo, different expression patterns of IGFBP7 are found in different tumor types." (PMID 24427302, 2014). "We have presented data indicating the mechanism of how IGFBP7 may be involved in this interaction, and this interaction, emphasizing the involvement of tumor stromal fibroblasts, could form the focus of a novel therapeutic approach to the management of cancer." (PMID 24427302, 2014). "We demonstrate that Imaginal morphogenesis protein-Late 2 (IMP-L2), a secreted protein and the fly homologue of the human IGFBP7 tumour suppressor, is capable of binding at least two of the seven Drosophila insulin-like peptides (DILPs), namely native DILP2 and DILP5 as present in the adult fly." (PMID 21108726, 2011). "Notably, IGFBP7 has received attention as a potent secreted tumour suppressor acting in an autocrine/paracrine manner to block melanoma genesis." (PMID 21108726, 2011). "Data suggest that IGFBP7 in the blood vessels of tumors may lead to a unique tumor vasculature with characteristics significantly different from those of normal vasculature." (PMID 21197468, 2011). "Tumour targeting by Cy5.5-labelled anti-IGFBP7 sdAb as well as by anti-IGFBP7 sdAb conjugated to PEGylated Fe3O4 nanoparticles (NPs)-Cy5.5 were assessed in U87MG.EGFRvIII tumour-bearing mice in vivo using optical imaging and in brain sections using fluorescent microscopy." (PMID 20959824, 2010). "The microarray analysis identified that insulin-like growth factor (IGF)-binding protein 7 (IGFBP7), which has been reported to have a tumour-suppressive activity through the induction of apoptosis in some cancers, was a key gene related to the response to this therapy." (PMID 20407444, 2010). "The downregulation of HSP60 induced by IGFBP7 may be, at least in part, responsible for IGFBP7's tumor suppressive biological behaviour in CRC." (PMID 20433702, 2010).
tumor (continued). "Additionaly, we examined binding at the gene promoter of insulin-like growth factor binding protein 7 (IGFBP7), a tumour-related soluble factor whose transcript was highly upregulated in our microarray analysis of SDHB-deficient cells, and which has been shown to be under epigenetic control." (PMID 19849834, 2009). "Various lines of evidence suggest that IGFBP7 inhibits tumor progression." (PMID 19019211, 2008). "In addition, recombinant IGFBP7 suppresses the growth of cultured human tumor cells through a mechanism that involves an increase in the number of cells in the G1 phase of the cell cycle." (PMID 19019211, 2008). "Furthermore, IGFBP-7 is suspected to be a tumor suppressor in a variety of human organs, including breast, lung and colon." (PMID 18412985, 2008). "Not only have known tumor suppressor genes like Cdkn2a (p16), Itga4 (α 4-integrin), and Igfbp7 been identified as targets of aberrant methylation in cancer by RLGS, but also novel tumor suppressor genes such as TCF21, SLC5A8, ID4, BMP3B, and SOCS1 have been identified by RLGS." (PMID 18053125, 2007). "Moreover, there is a link between IGFBP7 and the tumor immune microenvironment." (PMID 40224214, 2025). "Likewise, an ambiguous role of IGFBP7 was reported in tumor angiogenesis." (PMID 39045455, 2024). "Besides, IGFBP7 can impact the behavior of tumor cells through various mechanisms, including the induction of cell senescence and apoptosis, as well as the inhibition of tumor proliferation." (PMID 39764614, 2024). "Furthermore, IGFBP7 may exert different functions in various cell types, with IGFBP7 signaling in CAFs or tumor vasculature overriding signaling in tumor cells and vice versa." (PMID 39045455, 2024). "Hence, the indirect effects of IGFBP7 on tumor vasculature must also be considered, where IGFBP7 signaling on tumor cells may enhance or reduce their expression of pro-angiogenic factors (Chen R.-Y." (PMID 39045455, 2024). "Hence, reduced tumor growth may at least be partially attributed to reduced revascularization due to IGFBP7 overexpression." (PMID 39045455, 2024). "Additionally, IGFBP7 expression was correlated with the expression of tumour MRGs in both datasets." (PMID 39351597, 2024). "In addition, IGFBP7 was also highly expressed in tumours in another STAD dataset, GSE29272." (PMID 39351597, 2024). "However, other studies have shown that IGFBP7 plays an adverse role in some tumours." (PMID 39351597, 2024). "Some literature also reported that IGFBP7 could also exert tumor inhibition function." (PMID 37660019, 2023). "Furthermore, we investigated the effect of IGFBP7 on tumor growth." (PMID 37568781, 2023). "Similarly, IGFBP7 could enhance the tumor cells’ ability to grow on plates and form spheres, indicating a positive effect on the cloning and growth ability of GC cells." (PMID 37568781, 2023). "Moreover, IGFBP7 and integrin αvβ3 were upregulated in the tumor vasculature." (PMID 37660019, 2023). "Recently, Sun and colleagues demonstrated that CD93 interacting with its receptor insulin-like growth factor binding protein 7 (IGFBP7) could contribute to abnormal tumor vasculature in human umbilical vein endothelial cells and influence tumor growth in in vitro murine KPC model." (PMID 36761750, 2023). "However, T cells recognition and tumor cell killing were lower in the high-IGFBP7 group." (PMID 35812369, 2022). "However, while a tumor suppressive role of IGFBP-7 has been shown for epithelial-like tumor cells, others have shown tumor promoting properties and stimulation of anchorage-independent growth in epithelial cells with an epithelial-to-mesenchymal (EMT) phenotype and in malignant mesenchymal cells." (PMID 33767994, 2021). "Therefore, IGFBP-7 is also considered to play a major role as a tumor suppressor." (PMID 31661774, 2019). "Therefore, we speculate that TGF-β secreted by cancer cells promoting IGFBP7 expression in fibroblasts may lessen the tumor suppressor role for fibroblasts in tumor tissue." (PMID 24427302, 2014).
tumor (continued). "In addition, the expression pattern of IGFBP7 varies with tumor types." (PMID 20158915, 2010). "CONCLUSION: Endothelial cell-derived IGFBP7 suppresses CRC progression via the EGR1/TGF-β1 pathway, while VAPA-mediated lysosomal degradation limits its tumor-suppressive function." (PMID 41692778, 2026). "CAFs promote tumor invasion and metastasis by promoting the release of FGF2 by secreting insulin-like growth factor-binding protein 7 (IGFBP7), which in turn affects the polarization of TAMs towards the M2 type and their infiltration into tumor tissue." (PMID 40038745, 2025). "Dysregulated expression of tumor suppressor molecules such as CD93 and its ligand IGFBP7 contributes to pathological tumor vasculature formation." (PMID 41281945, 2025). "More importantly, we demonstrated that IGFBP7 modulates the crosstalk between STAD cells and macrophages, a key component of the tumour microenvironment." (PMID 39788916, 2025). "IGFBP-7 is upregulated in the angiogenic vasculature during physiological vessel formation via VEGF-A and pathological processes such as tumor neovascularization." (PMID 41226289, 2025). "Curiously, IGFBP-3 and IGFBP-7 have been found to be induced by TGF-β1 expression and activate TGF-β receptors in a tumor context." (PMID 41226289, 2025). "The identification cohort showed the overexpression of IGFBP7 and ANXA1 regarding all tumor stages versus controls, in exosomes isolated from serum." (PMID 38893148, 2024). "Forced overexpression of IGFBP7 in HCC cells induced senescence, and profoundly suppressed in vivo tumor growth." (PMID 39045455, 2024). "Chemotherapy triggers tumor endothelial cells to suppress IGFBP7, and the upregulation of IGF1 activates the FGF4-FGFR1-ETS2 pathway and accelerates the conversion of tumor cells to chemo-resistant tumor stem-like cells." (PMID 38576482, 2024). "CD93 is a receptor for insulin-like growth factor binding protein 7 (IGFBP7, also known as angiomodulin), which is secreted by tumor vessels and contributes to vascular abnormalities." (PMID 38441970, 2024). "Our results showed increased levels of IGFBP7 and ANXA1 in LSCC compared to controls for all tumor stages." (PMID 38893148, 2024). "When HCC cells overexpressing IGFBP7 were implanted in a chicken chorioallantoic membrane (CAM) assay, angiogenesis was significantly reduced in the formed tumor masses." (PMID 39045455, 2024). "In particular, IGFBP7 is a protein positively and significantly correlated with CD93 that has been identified to be up-regulated in tumor blood vessels and able to promote vascular angiogenesis." (PMID 37483608, 2023). "The expression of IGFBP7 mRNA was significantly higher in stages II, III, and IV of GC than in stage I and a similar result was observed in the depth of tumor invasion in GC TNM staging." (PMID 37568781, 2023). "Third, the expression levels of CD93, IGFBP7, and MMRN2 in various solid tumors and their relationship with the clinical characteristics of tumor patients should be further investigated." (PMID 37660019, 2023). "Further analysis of paired tumor and normal samples from the TPM-formatted TCGA-STAD dataset revealed that IGFBP7 mRNA expression levels were also elevated in GC." (PMID 37568781, 2023). "Interaction with its ligand, insulin-like growth factor binding protein 7 (IGFBP7), contributes to the formation of a dysfunctional tumor vessel structure." (PMID 36901858, 2023). "Sun and colleagues found that insulin-like growth factor binding protein 7 (IGFBP7), an extracellular matrix (ECM) protein present on tumor vasculature, interacts with CD93, contributing to an abnormal tumor vasculature." (PMID 37443812, 2023). "Western blot results showed that S1PR1, cyclin B1, PDK1, and lamin B1 protein levels were significantly decreased, whereas P21, P62, histone H3, IGFBP7, and PAI-1 protein levels were significantly increased in S1PR1 knockout tumor tissue." (PMID 37828220, 2023).
tumor (continued). "IGFBP7 is primarily induced by the TGF-β1 pathway and secreted into the matrix by CAFs, potentially affecting tumor cells." (PMID 37568781, 2023). "This study clarified that in the tumor microenvironment, tumor cell-derived TGF-β1 induces the appearance of an IGFBP7+ CAFs subgroup, and its higher IGFBP7 extracellular secretion level accelerated the progression of tumors." (PMID 37568781, 2023). "Compared with normal tissues, IGFBP7, LBH and TFPI are low expressed in tumor tissues (P < 0.05), while KRT18, UBE2C and UBE2S were highly expressed in tumor tissues (P < 0.05)." (PMID 38077434, 2023). "The tumour endothelial cells expressed PLVAP and IGFBP7, and oxidative phosphorylation, glycolysis, and gluconeogenesis were upregulated in the metabolic activity analysis." (PMID 36077754, 2022). "Furthermore, we offer the following conjecture regarding why higher IGFBP7 expression is accompanied by more enriched TILs: the increases in tumor vascular permeability can result in leakage through the vessel wall, which allows the tumor cells and TILs to leave the tissue more easily." (PMID 35812369, 2022). "The mechanisms mediating the bone- and neoplasm-forming effects of PTH remain incompleted understood, few studies on the role of Insulin-like growth factor-binding protein 7 (IGFBP7) in mediating the anabolic effects of PTH has been reported." (PMID 35462909, 2022). "Cox multivariate regression analysis showed that besides tumor stages, IGFBP1 and IGFBP7 were independent predictors in STAD patients." (PMID 34745945, 2021). "Age-adjusted geometric means with 95% Wald confidence intervals (CIs) of IGF-I, IGFBP-3, IGFBP-7, and IGF-I/IGBP-3 molar ratios in relation to patient and tumor characteristics." (PMID 33767994, 2021). "Insulin-like growth factor-binding protein 7 (IGFBP7), which has several characteristics of a potential tumor suppressor, is also decreased in brain-specific metastases." (PMID 33466236, 2021). "For instance, it is plausible that the downregulation of 3 upstream regulators of SOD2 (IGFBP7, KL, BTG2), which are potential tumor suppressors, leads to an increase in SOD2 when the malignancy of IPMN worsens." (PMID 32842508, 2020). "IGFBP7 and MDK expressed by tumor cells and CAFs promote tumor progression and relapse by enhancing cancer stemness, EMT, extracellular matrix remodeling, and angiogenic activity." (PMID 32460812, 2020). "The tumor cells in cluster B showed similar characteristics to those of tipifarnib-resistant tumor cells, including downregulation of the RAS and MAPK signaling pathways and upregulation of IGFBP7, MDK, and B2M mRNA." (PMID 32460812, 2020). "The basal tumor cluster #3 demonstrated transcriptional downregulation of HRAS; cell dormancy; and a higher expression of IGFBP7, MDK, and B2M, recapitulating those of the tipifarnib-resistant (or cluster B) BC159-T#3 PDX tumor cells." (PMID 32460812, 2020). "Chemotherapy triggers TECs to suppress IGFBP7, and the upregulation of IGF1 activates the FGF4-FGFR1-ETS2 pathway in TECs and accelerates the conversion of tumor cells to chemoresistant tumor stem-like cells." (PMID 31600937, 2019). "Within the group of 17 proteins, four exhibited the most pronounced expression difference: IGFBP7, S100A9 and IL-10 were found strongly up-regulated in tumor, while MUC6 was markedly less abundant compared to the reference tissue." (PMID 27600085, 2016). "Since aberrant IGFBP7 expression was observed in a variety of neoplasia and was relevant for prognosis in T-ALL, we investigated the functional role of IGFBP7 in Jurkat and Molt-4 cells as in vitro models for T-ALL." (PMID 26450156, 2015). "To confirm the presumption, we studied IGFBP7, caspase-3, VEGF expression and apoptosis in tumor homograft tissues." (PMID 20158915, 2010). "In this study, a llama anti-IGFBP7 single-domain antibody (sdAb) was developed and assessed in a mouse model of GBM for its ability to detect tumour vessels after in vivo administration." (PMID 20959824, 2010).